NANOG (Nanog homeobox)
Diseases named in the same sentence as NANOG in open-access papers (continued):
Sharing a sentence is not in itself a finding about the gene and the disease.
ovarian carcinoma (72 papers, 2010 to 2026). A malignant neoplasm originating from the surface ovarian epithelium. "An increase in gene and protein levels of NANOG in ovarian cancer cells was associated with higher sphere-forming capacities and drug and apoptosis resistance our results." (PMID 37189618, 2023). "Numerous studies have also demonstrated that OCT4 and NANOG are associated with chemoresistance in ovarian cancer." (PMID 36551731, 2022). "Samples of metastatic foci as well as ovarian cancer cell lines with features associated with metastasis have both been found to have high NANOG expression." (PMID 36114703, 2022). "Even more, the overexpression of NANOG in the epithelial ovarian cancer was associated with a high grade tumor, advanced clinical stage of disease, resistance to chemotherapy, and shorter patient survival rate." (PMID 28231820, 2017). "Therefore, markers, such as OCT3/4, NANOG, and Vimentin, can be used as diagnostic markers for ovarian cancer cell detection." (PMID 33671303, 2021). "To address this deficiency, we investigated SOX2, OCT4, and NANOG expression in a panel of ovarian cancer cell lines to identify correlations with growth properties, spheroid-forming potential, traditional TIC marker expression, tumorigenesis, and chemoresistance." (PMID 33445692, 2021). "NANOG is another stem cell-associated gene that is associated with ovarian cancer." (PMID 23528891, 2013). "ALKBH5 raised NANOG expression through the demethylation of NANOG mRNA, which accelerated ovarian cancer development." (PMID 40001461, 2025). "We previously showed that SOX2, relative to OCT4 or NANOG, is a better marker of drug-resistant CSCs in ovarian cancer." (PMID 39287565, 2024). "DCs loaded with Nanog homeobox (NANOG) peptide can potentially evoke strong T-cell-mediated anti-tumor response against ovarian cancer cells." (PMID 36613838, 2022). "Given that NANOG expression stimulates ovarian cancer cell invasion and migration, we subsequently explored the AMPK/mTOR signalling pathway, which plays an important role in tumour development and metastasis." (PMID 36114703, 2022). "Studies have found that in ovarian cancer, the core cytokine NANOG is a key target to promote the development of ovarian cancer." (PMID 35707365, 2022). "Increased expression of OCT4 and NANOG is a prognostic factor in several cancers, including breast, colorectal, and ovarian cancer." (PMID 36551731, 2022). "In this study, we investigated the clinicopathological features and prognostic significance of NANOG and pAMPKα in ovarian cancer." (PMID 36114703, 2022). "Functionally, knockdown of NANOG in ovarian cancer cell lines hindered cell migration and invasion, as well as the EMT process via the AMPK/mTOR signalling pathway." (PMID 36114703, 2022). "In the present study, we investigated the clinical relevance of NANOG expression in ovarian cancer and the molecular mechanism by which NANOG mediates EMT process." (PMID 36114703, 2022). "In ovarian cancer, the androgen receptor contributes to the function of NANOG, which subsequently promotes ovarian CSC maintenance." (PMID 36114703, 2022). "In ovarian cancer cell lines, siRNA‐mediated NANOG knockdown diminished migration and invasion properties by regulating the EMT process via the AMPK/mTOR signalling pathway." (PMID 36114703, 2022). "SOX2, OCT4, and NANOG are enriched in ovarian cancer spheroids and correlate with tumor-initiating cell markers, CD117 and ALDH/CD133." (PMID 33445692, 2021). "NANOG expression increased after mRNA demethylation, consequently enhancing the aggressiveness of ovarian cancer cells." (PMID 32329191, 2020). "To prove that ALKBH5 affects the methylation of NANOG, we performed m6A‐Seq to map the m6A modification in co‐cultured ovarian cancer cells." (PMID 32329191, 2020). "In contrast to LAMA4, CA11, and MEDAG, the 2 mRNAs, SPINT2 and NANOG, were found to be increased in ovarian cancer ascites compared to peritoneal fluid EVs." (PMID 29499737, 2018).
ovarian carcinoma (continued). "Functional experiments showed that NANOG expression is required for ovarian cancer migration and invasion, through regulation of E-Cadherin and FOXJ1." (PMID 29389895, 2018). "Three mRNAs, CA11, LAMA4, MEDAG, were .01–.28-fold lower expressed and two mRNA, SPINT2 and NANOG, were 3.2–5.8-fold higher expressed in ovarian cancer ascites versus peritoneal fluid EVs." (PMID 29499737, 2018). "NANOG expression in primary ovarian cancers was found to be correlated with disease grade, reduced chemosensitivity and poor survival." (PMID 29389895, 2018). "Overexpression of NANOG, SOX2 and OCT4 have been linked to therapy resistance, reduced overall survival and increased progression in ovarian cancer, head and neck, breast, renal and rectal cancer patients." (PMID 30513961, 2018). "The ABCB1 transporter increases chemoresistance in these ovarian CSCs and NANOG promotes the epithelial to mesenchymal transition (EMT) in ovarian cancer." (PMID 30042330, 2018). "NANOG is overexpressed in ovarian carcinoma, colon carcinoma and ESCC, and enhances proliferation and self-renewal of pluripotent stem cells." (PMID 28404917, 2017). "In ovarian cancer, stable knockdown of NANOG led to decreased cell proliferation, migration, and invasion, which were accompanied by increased expression of E-cadherin and FOX-related genes including FOXJ1, results consistent with our findings." (PMID 27588392, 2016). "The experimental results from the literature indeed showed that cancer cells in epithelial ovarian cancers express a strong cytoplasmic expression of pluripotency-related NANOG." (PMID 26940129, 2016). "The connection between JAK2/STAT3 pathway activation and CSCs has been highlighted in a previous work on ovarian cancer, where the SC marker CD44 together with the embryonic SC marker NANOG have been associated with the activation of STAT3." (PMID 26312765, 2015). "Depletion of NANOG inhibits the proliferation, migration, and invasion of ovarian cancer cells with concomitant increases in the mRNA levels of E-cadherin, caveolin-1, FOXO1, FOXO3a, FOXJ1 and FOXB1 in these cells." (PMID 23528891, 2013). "Conversely, proliferation, migration and invasion are enhanced in ovarian cancer cells overexpressing NANOG." (PMID 23528891, 2013). "Our study shows that ovarian cancer SP cells express the embryonic stem cell markers, NANOG, OCT4, STELLAR, and ABCG2/BCRP1." (PMID 20354527, 2010). "In ovarian cancer, high expression of TLR4 could activate NF-κB signaling pathway, thus up-regulated ALKBH5 to influence the m6A methylation of NANOG, which further promoted carcinogenesis in ovarian cancer." (PMID 38637813, 2024). "We have previously shown that SOX2 is a marker of chemoresistance and recurrence in ovarian cancer; thus, we next sought to characterize changes in SOX2, OCT4, and NANOG expression in ovarian cancer cells indirectly co-cultured with differentially polarized macrophage populations." (PMID 39287565, 2024). "NANOG depletion reduced ovarian cancer cell proliferation, invasion, and stem-like characteristics." (PMID 37189618, 2023). "Interestingly, AhRR and PPP1R3C expression significantly correlates with stemness markers’ (ALDH1A1, CD44, ABCG2, NANOG) expressions in ovarian cancer tissues (p < 0.01)." (PMID 37511212, 2023). "Given that AMPK is associated with cancer metastasis, we hypothesized that NANOG modulates AMPK signalling to regulate the EMT process and promote ovarian cancer metastasis." (PMID 36114703, 2022). "Moreover, Hexokinase 2 regulates the metastasis, invasion, and cell stemness of ovarian cancer cells through the FAK/ERK1/2/MMP9/NANOG/SOX9 signal transduction pathways." (PMID 34596006, 2021). "In contrast, trametinib treatment of PEO4 cells for 10 h significantly promoted the expression of cell stemness regulators SOX2, NANOG, POU5F1 (OCT4), and two ALDH1A homologs associated with elevated chemoresistance and the stem-like phenotype of ovarian cancer cells." (PMID 33803586, 2021).
ovarian carcinoma (continued). "SOX2, but not OCT4 or NANOG, has been implicated in early tumor initiation and plays a more substantial role in tumor relapse in ovarian cancer patients." (PMID 34064635, 2021). "In conclusion, NANOG was a downstream target of ALKBH5 that might promote ovarian cancer development through demethanizing NANOG." (PMID 32329191, 2020). "Furthermore, NANOG interacts with androgen receptors to promote the proliferation and migration of ovarian cancer stem cells." (PMID 33336042, 2020). "NANOG has been widely used as a stem cell marker, is associated with stemness maintenance and EMT acceleration, and is taken as an indicator of a poorer prognosis in ovarian cancers." (PMID 30518424, 2018). "Similarly, CSCs isolated from ascites derived from ovarian cancer patients showed elevated NANOG expressions." (PMID 30518424, 2018). "NANOG has also been detected in different types of tumors, including the epithelial ovarian cancer." (PMID 28231820, 2017). "The results indicate that NANOG alone or in combination with SOX2 may contribute to the transformation of ovarian endometriosis to ovarian cancer." (PMID 24884521, 2014). "Additionally, we identified a novel mechanism by which NANOG increases the metastatic potential of ovarian cancer cells by regulating the AMPK/mTOR pathway, which might foster new therapeutic strategies for the treatment of ovarian cancer." (PMID 36114703, 2022). "With the deepening of the research on the mechanism of drug resistance of ovarian cancer cells, VEGF, NANOG, epithelial cadherin, Snail, etc., have been found to play an important role in drug resistance of ovarian cancer, and are expected to become new targets for the treatment of ovarian cancer." (PMID 35548853, 2022). "In addition, c-MYC expression has been most often proposed as a general feature of the CSCs of various cancers including breast, prostate, esophagus and tongue, and the expression of c-MYC together with NANOG has been previously noted as a feature in a population of ovarian cancer cells." (PMID 30518424, 2018). "The marker NANOG has been analyzed on account of our previous finding that this marker is strongly expressed in small stem cells from adult human ovaries, and its expression in cancerous ovaries has already been related to ovarian cancer in terms of poorer outcome in ovarian epithelial malignancies." (PMID 26940129, 2016). "Additionally, NANOG expression is negatively correlated with postoperative survival in patients with lung and ovarian cancer, and increased NANOG expression in human prostate cancer tissues is correlated with an increased Gleason score, which is an indicator of poor prognosis." (PMID 26087476, 2015). "The heatmap revealed that PIWIL1, DNMT3B, OCT4, NANOG, and CDH2 were increased in most ovarian cancer samples, while CDH1 was downregulated, thus delineating clear expression differences between cancer and control samples." (PMID 41596471, 2026). "In CD133+ ovarian cancer cells, LINC00115 silencing decreases the expression of CD44, CD133, and NANOG." (PMID 39967908, 2025). "In our previous study, we checked the expression of ovarian cancer stemness markers ALDH, CD44, ABCG2, and NANOG and spheroids’ clonogenic nature through PKH staining." (PMID 39596687, 2024). "We found that ovarian cancer cells treated with carboplatin in combination with CCL2/MCP-1 for 48 hours had increased SOX2, OCT4, and NANOG gene expression and greater spheroid formation ability relative to carboplatin or CCL2/MCP-1 treatment alone." (PMID 39287565, 2024).
ovarian carcinoma (continued). "Chemoresistant ovarian cancer cells also have higher expression of cancer stem cell markers, including OCT4 and NANOG.Similarly, OCT4 and NANOG expression was upregulated in parallel with increased chemoresistance in FBS− GF− MKN-45 cells." (PMID 37529165, 2023). "Of interest, NANOG expression correlated positively with levels of total and phosphorylated STAT3, suggesting a role for NANOG-mediated EMT and drug-resistance through the activation of the STAT3 pathway in epithelial ovarian cancer." (PMID 37189618, 2023). "FOXP1 functions as an oncogene in epithelial ovarian cancer cells by promoting the CSC-like characteristics, while its overexpression led to an up-regulated expression of ABCG2, OCT4, NANOG, and SOX2 genes and protected cells against apoptotic cell death." (PMID 37189618, 2023). "Firstly, we analyzed the expression of known ovarian cancer stemness markers: ALDH1, CD44, ABCG2, and NANOG." (PMID 37511212, 2023). "To test the relevance of the Src pathway in the acquisition of a CSC phenotype, we generated ovarian cancer tumorspheres in the presence of PP2, a Src inhibitor which suppressed the expression of two master regulators of the CSC phenotype, CD133 and NANOG." (PMID 37189618, 2023). "NANOG engages with tumour initiation and metastasis by regulating the epithelial–mesenchymal transition (EMT) in epithelial ovarian cancer (EOC)." (PMID 36114703, 2022). "The expression level of CD133 is elevated in sphere-forming and drug-resistant populations of ovarian cancer cells, which exhibit chemoresistance and tumorigenesis in vivo and increased levels of stemness markers such as OCT4, SOX2, and NANOG." (PMID 34064635, 2021). "Bai S’s study had also proven that EGFL6 promotes the asymmetric division of cancer stem-like cells in ovarian cancer, consistent with this research’s result that EGFL6 could keep the cell stemness by regulating the expression of cancer stem cell associated genes, POU5F1, NANOG, and LIN28." (PMID 33726836, 2021). "A side population of cells expressing NANOG, OCT4 and ABCG2/BCRP1 was isolated from ovarian cancer cell lines and ascites of ovarian cancer patients, and was found to have increased tumourgenicity and chemoresistance." (PMID 34283069, 2021). "CD117+ ovarian cancer cells overexpress SOX2, octamer-binding transcription factor 4 (OCT4), and NANOG, which are CSC markers involved in stemness and chemoresistance." (PMID 34064635, 2021). "Taken together, these data highlight the heterogeneous expression of TIC genes across ovarian cancer cell lines and suggest that HGSOC lines have consistent enrichment of SOX2, OCT4 and NANOG that correlates with specific TIC markers." (PMID 33445692, 2021). "To this end we employed RT-qPCR analysis, western blot and/or immunofluorescence to assess the expression of CD44, NANOG, OCT4 and SOX2, regarded as putative ovarian cancer stem cells markers." (PMID 33250051, 2020). "We analysed the effect of tumour environment on the expression of NANOG/OCT4/SOX2, three core pluripotency factors in human ovarian cancer cells." (PMID 32329191, 2020). "Ovarian cancer stem cells (CSCs), also known as cancer-initiating cells, are characterized by cell surface expression of CD24, CD44, CD117 (KIT), SOX2, and NANOG." (PMID 32823589, 2020). "At the same time, the expression level of ALKBH5 was significantly increased in SKOV‐3 and Ishikawa co‐cultured cells; meanwhile, all the expression levels of NANOG, SOX‐2 and OCT‐4 increased in ovarian cancer tissues, but fell in ovarian cancer cell lines." (PMID 32329191, 2020). "GEPIA further revealed a significant clinical correlation between NANOG, OCT4, KLF4, SOX9, and CD117 and HK2 expression (p < 0.05) in ovarian cancer clinical samples." (PMID 31212816, 2019).
ovarian carcinoma (continued). "In conclusion, HK2, which is regulated by the tumor microenvironment, controls lactate production and contributes to ovarian cancer metastasis and stemness regulation via FAK/ERK1/2 signaling pathway-mediated MMP9/NANOG/SOX9 expression." (PMID 31212816, 2019). "In ovarian cancer cells isolated for the SP, Notch pathway genes (FPTG, ST3GAL6, and ADAM19), stem cell markers NANOG and OCT4, and three ABC transporter genes (ABCG2 [both lines], ABCC4 [SKOV3 only], and ABCB1 [A224 only]) were induced." (PMID 30042330, 2018). "The predictors, LAMA4, CA11, MEDAG, NANOG, SPINT2, let-7b, miR23b, and miR29a were found to be sufficient to classify 87.5% and 100% of ovarian cancer (n = 8) and disease control (n = 10) groups, respectively." (PMID 29499737, 2018). "Overexpression of Notch3 in ovarian cancer cell lines (IOSE-80pc and MPSC1) enhances expression of stem cell markers (NANOG, OCT4, and SOX2) and increases expression of the ABCB1 transporter protein." (PMID 30042330, 2018). "We found that SGC0946 and EPZ004777 inhibited expression of DOT1L-targeted genes (MEIS1 and NANOG) in a dose-dependent manner, a finding which confirms the inhibitory effect of DOT1L activity in ovarian cancer cells." (PMID 29712898, 2018). "To validate that VJ targets other CSC populations in addition to ALDH1+ CSC population, we examined the effect of VJ on expression of genes for NANOG, LGR5 and OCT4, reported to be present in ovarian cancer." (PMID 29190952, 2017). "In ovarian cancer, the most common CSCs identified include CD24, CD34, CD44, CD117, ALDH1, EpCAM, SSEA4, NANOG, MYD88, and SOX2 positive cells." (PMID 29190952, 2017). "The first report of CSCs in epithelial ovarian cancer showed expression of OCT4 and NANOG in self-renewing spheroids." (PMID 26654944, 2016). "Leveraging our previous success in the enrichment of CSCs in triple-negative breast cancer using a NANOG promoter-driven green fluorescence protein (GFP) reporter system, we applied this to ovarian cancer cell lines." (PMID 27105520, 2016). "In the current study, we showed FOXP1 up-regulated transcription activity of ABCG2, OCT4, NANOG, and SOX2 in A2780 ovarian cancer cells." (PMID 26654944, 2016). "Consistent with this idea OCT4, NANOG and SOX2 are expressed in ovarian CPCs, and the enforced expression of OCT4 or NANOG enhances the malignancy of ovarian carcinoma cell lines." (PMID 26503466, 2015). "Recent work on epithelial ovarian cancer has shown that pluripotency TFs, such as OCT4 and NANOG, are overexpressed in poorly differentiated epithelial ovarian cancers." (PMID 21952072, 2011). "We found that exposure to M0, M1, or M2 macrophages for 48 hours did not significantly affect SOX2, OCT4, and NANOG expression in CAOV4 or OVCAR8 ovarian cancer cells." (PMID 39287565, 2024). "The results of various studies have suggested that the expressions of stem cell markers, such as NANOG, SOX2, forkhead-box protein M1 (FOXM1), and OCT4, in ovarian cancer mirror their tumorigenic potential, as well as resistance to paclitaxel, cisplatin, methotrexate, and adriamycin cells." (PMID 38201468, 2023). "Our data showed that siRNA‐mediated NANOG knockdown drastically inhibited cell migration and invasion as well as the EMT process by activating the AMPK/mTOR signalling pathway in SKOV‐3 and A2780 ovarian cancer cells." (PMID 36114703, 2022). "This might be due to NANOG promotes the occurrence and stemness of ovarian cancer via glycolytic enzyme HK2 in ovarian cancer." (PMID 35022030, 2022). "Furthermore, we evaluated the relationship between NANOG and AMPK/mTOR signalling pathway and examined the clinical and prognostic significance of pAMPK in ovarian cancer." (PMID 36114703, 2022). "In addition to ABCG2/BCRP1, many embryonic stem cell markers, such as NANOG, OCT4 and STELLAR, were expressed in SP cells of ovarian cancer." (PMID 35982417, 2022).